PPARA (peroxisome proliferator activated receptor alpha)
Diseases named in the same sentence as PPARA in open-access papers (continued):
Sharing a sentence is not in itself a finding about the gene and the disease.
Ureteral obstruction (5 papers, 2012 to 2025). Obstruction of the flow of urine through the ureter. "Here, we examine whether a novel selective PPARα modulator, pemafibrate modulates renal injury in a model of unilateral ureteral obstruction (UUO)." (PMID 39887648, 2025). "These tubular protective effects of PPARα were detected in various types of tubulointerstitial injury models, such as protein-overload nephropathy (the toxicity of excess fatty acids), unilateral ureteral obstruction, 5/6 nephrectomy, ischemia/reperfusion injury, and cisplatin injury." (PMID 22675338, 2012). "Decreased expression of PPARα after renal IRI can promote fibrosis, and overexpression of PPARα induced by miR-21 deletion can prevent ureteral obstruction-induced injury and fibrosis of the kidneys." (PMID 35646989, 2022).
Abdominal obesity (4 papers, 2016 to 2025). Excessive fat around the stomach and abdomen. "Another study showed that PPARα-deficient mice developed abdominal obesity." (PMID 27434237, 2016). "Notably, GFT505 (a dual PPARα/δ agonist) has been demonstrated to improve lipid and glucose homeostasis in patients with abdominal obesity." (PMID 33494735, 2021).
anemia (4 papers, 2020 to 2022). A reduction in the number of red blood cells, the amount of hemoglobin, and/or the volume of packed red blood cells. "Here, we show for the first time that gemfibrozil treatment leads to anemia and leukopenia via peroxisome proliferator-activated receptor alpha in mice." (PMID 32708962, 2020). "Considering that gemfibrozil may lead to anemia and that gemfibrozil acts via peroxisome proliferator-activated receptor alpha, we treated wild-type and peroxisome proliferator-activated receptor alpha-knockout mice with gemfibrozil for four consecutive days." (PMID 32708962, 2020). "According to its biological function in the immune system, PPARA could be protecting the depletion of the host’s cells from its own immune system during parasitic manipulation of immune responses, possibly controlling anaemia in N’Dama after trypanosome infection." (PMID 33429951, 2021). "However, PPARα wild type but not PPARα−/− respond to PPARα agonists under induced acute haemolytic anemia." (PMID 35269942, 2022).
Arrhythmia (4 papers, 2016 to 2023). Any cardiac rhythm other than the normal sinus rhythm. "Alternatively, while Valsartan preserved cardiac function, it was nearly devoid of conduction abnormalities, arrhythmias, and reduced RVF, and myocardial samples showed increased PPARα nuclear levels, active β-catenin, and Wnt-mediated mRNA transcription." (PMID 36430389, 2022).
bacterial sepsis (4 papers, 2020 to 2024). "Mice treated with the PPARa agonist pemafibrate are protected against bacterial sepsis as it improves hepatic PPARa function and reduces lipotoxicity and tissue damage." (PMID 38727856, 2024). "In addition, treatment of mice with the PPARα agonist pemafibrate protects against bacterial sepsis by improving hepatic PPARα function, reducing lipotoxicity and tissue damage." (PMID 31916705, 2020). "Hepatic PPARα was previously shown to be crucial for survival during bacterial sepsis since mice lacking PPARα in the liver were sensitized to a lethal E. coli challenge and showed severe metabolic and inflammatory reprogramming." (PMID 31916705, 2020). "The absence of PPARα resulted in more rapidly increasing intracellular bacterial load in macrophages, heavier bacteremia in the lungs, spleen, and liver, and a significantly higher level of inflammatory cytokines TNFα and IL-6 in the lungs, as compared to wt PPARα mice." (PMID 34638886, 2021).
brain tumor (4 papers, 2010 to 2024). "Consistent with this, one report demonstrated a synergistic effect of PPARα agonist and NAC in control of brain tumor cells." (PMID 23867003, 2013).
chronic hepatitis C (4 papers, 2009 to 2018). "By contrast, Bezafibrate, via inhibition of proliferator-activated receptors (PPARα), was seen to significantly increase interferon-γ in patient with chronic hepatitis C after 4 months of therapy." (PMID 28628632, 2017). "The level of PPARα mRNA has been measured in the liver of chronichepatitis C patients also in another study, and found to be profoundlysuppressed (about 85% compared to control livers)." (PMID 19132131, 2009).
corneal diseases (4 papers, 2020 to 2024). "In the disease state of corneal diseases, the therapeutic roles of PPARα activation have been studied." (PMID 34833044, 2021). "Taken together, the therapeutic roles of PPARα activation in corneal diseases have been established." (PMID 34833044, 2021). "The combination ophthalmic solution of fenofibrate and pioglitazone suppressed inflammation, neovascularization, and fibrotic changes by a dual therapeutic effect of the PPARα and PPARγ agonists in the alkali-burned cornea, suggesting a new candidate therapeutic strategy for corneal disease." (PMID 32707656, 2020).
gallstones (4 papers, 2018 to 2025). Solid crystalline precipitates in the biliary tract, usually formed in the gallbladder, resulting in the condition of cholelithiasis. "Given its high selectivity for PPARα, pemafibrate may amplify these pathways and alter bile acid homeostasis, potentially increasing gallstone risk." (PMID 41368577, 2025).
glomerular disease (4 papers, 2014 to 2025). "Notably, PPARα has been shown to reduce the inflammatory response in LPS-treated mesangial cells, suggesting its potential role in glomerular diseases." (PMID 40282352, 2025). "Since synthetic agonists for PPARα and LXRα are reported to increase cholesterol efflux and ameliorate lipid-related glomerular disease, it can be speculated that these NHRs in mesangial cells represent therapeutic targets for treating glomerular injuries in DN." (PMID 24465611, 2014).
gout (4 papers, 2018 to 2025). A condition characterized by painful swelling of the joints, which is caused by deposition of urate crystals. "Another dual PPARα/γ agonist, oxeglitazar, whose development was halted in phase І clinical trials, is also used for gout treatment." (PMID 30060458, 2018). "The therapeutic targets through which Simiao decoction alleviated gouty arthritis were p-STAT3, APOB, CASP8, c-FOS, PPARα, FN1, and LPL." (PMID 32670069, 2020).
influenza (4 papers, 2011 to 2023). An acute viral infection of the respiratory tract, occurring in isolated cases, in epidemics, or in pandemics; it is caused by serologically different strains of viruses (influenzaviruses) designated A, B, and C, has a 3-day incubation period, and usually lasts for 3 to 10 days. "In contrast, in a mouse influenza model, administration of oseltamivir (antiviral) and fibrates (PPARα agonist) prolong survival time during lethal H7N9 infection." (PMID 35860381, 2022). "Using an in vitro polarization to the M2b subtype, enhancement of M2b (induced by immune complex/TLR ligand) polarization by PPARα agonist is intriguing because generation of anti-influenza IgG antibodies begins around day 7 post primary infection." (PMID 35860381, 2022). "While we observed a persistence of S. aureus in the lungs of influenza-infected mice, using an in vitro system, we determined that the anti-bacterial function of macrophages was greatly hindered due to PPARα activation." (PMID 35860381, 2022). "PPARα agonists may be useful for successful resolution during influenza infection." (PMID 35860381, 2022).
kidney failure (4 papers, 2019 to 2023). An acute or chronic condition that is characterized by the inability of the kidneys to adequately filter the blood. "PPARα knock-out mice are more susceptible to a lethal dose of LPS and bacterial infections, which is associated with increased kidney failure and heart injury." (PMID 37006237, 2023). "However, a majority of these drugs showed severe adverse effects, including heart failure, renal failure, urinary cancer, body weight gain, stroke, and anemia, necessitating the development of novel PPARα/γ dual agonists without side-effects." (PMID 30733541, 2019).
kidney stones (4 papers, 2016 to 2025). "To clarify the roles of PPARα and PPARγ in kidney stone formation, we first examined their expression using hyperoxaluric stone model mice." (PMID 27022389, 2016). "Since PPARα and PPARγ are differentially expressed in the kidneys, it is reasonable that these two effectors play opposing roles in tubular cell CaOx crystal deposition and should be considered when treating MetS patients with kidney stones." (PMID 27022389, 2016). "Although the exact role of PPARs in kidney stone pathogenesis is yet unknown, we revealed that PPARα and PPARγ exhibit differential effects on this process in hyperoxaluric mice and rats." (PMID 27022389, 2016). "How PPARA expression changes PPARG expression and activity in the nephrolithiasis inflammatory fibrosis process is still unclear." (PMID 37569334, 2023).
Lewis lung carcinoma (4 papers, 2007 to 2021). "The absence of PPARα expression suppresses tumor growth of Lewis lung carcinoma cells." (PMID 33414412, 2021).
liposarcoma (4 papers, 2007 to 2023). A usually painless malignant tumor that arises from adipose tissue. "In addition, genes involved in receptor activity, signaling and lipid metabolism (some of which have previously been reported in liposarcoma) such as ACAA2, ARSA, DHRS3, PDE3A, and PPARA, were upregulated." (PMID 17359542, 2007). "PPARA and PPARG ligands, known as peroxisome proliferators, have been shown to induce cell cycle arrest at the G1 phase of the cell cycle to prompt the differentiation of liposarcoma, colon, prostate and BC cells, conferring a less malignant phenotype to the cells." (PMID 30974831, 2019).
liver cirrhosis (4 papers, 2022 to 2025). "Molecular docking performed on PPARα identified pharmacodynamic components of Rgkl like Quercetin and Kaempferol may be the key to ameliorate liver cirrhosis by modulating the lipid metabolism in LSECs." (PMID 41039598, 2025).
lupus nephritis (4 papers, 2012 to 2026). Glomerulonephritis in the context of systemic lupus erythematosus. "The NF-κB-suppressing effects of glomerular PPARα might be useful for the treatment of the various types of glomerulonephritis, including MsPGN, immune complex kidney disease, crescentic glomerulonephritis, and lupus nephritis, as well as metabolic abnormality-based glomerulonephropathy." (PMID 22675338, 2012).
lymphoma (4 papers, 2019 to 2025). A malignant (clonal) proliferation of B- lymphocytes or T- lymphocytes which involves the lymph nodes, bone marrow and/or extranodal sites. "As fibrates are PPARα agonists they edit the whole lymphoma tissue as PPARα is expressed on lymphoma and stroma cells." (PMID 35814409, 2022). "Given that EBV is associated with several other malignancies including nasopharyngeal carcinoma and lymphoma, future studies are needed to determine whether the miR-BART20-3p–PPARα regulatory axis operates similarly in other EBV-associated cancers." (PMID 40732023, 2025).
medulloblastoma (4 papers, 2012 to 2023). A malignant, invasive embryonal neoplasm arising from the cerebellum. "PPARα is expressed in medulloblastoma cells, and PPARα activation with fenofibrate inhibited cell proliferation in medulloblastoma cell lines." (PMID 35954274, 2022).
metastatic tumors (4 papers, 2014 to 2025). "Genetic alterations in metabolic genes associated with metastatic progression analyzed, revealed that genes involved in cellular fatty acid uptake (CAV1, CD36) and de novo lipogenesis (PPARA, PPARD, MLXIPL) were specifically amplified at higher frequencies in metastatic tumors." (PMID 28798698, 2017). "However, 6 genes were amplified at significantly higher frequencies in metastatic tumors: SCO2 (p = 1.1 × 10−9), MLXIPL (p = 2.1 × 10−4), PPARA (p = 1.2 × 10−10), PPARD (p = 4 × 10−15), CAV1 (p = 3.4 × 10−4) and CD36 (p = 3.5 × 10−4)." (PMID 26725848, 2016). "Instead, we observed significant amplification of PPARA and MXIPL in metastatic tumors which could upregulate the transcription of lipogenesis genes." (PMID 26725848, 2016). "However, genes involved in cellular FA uptake (CAV1, CD36) and de novo lipogenesis (PPARA, PPARD, MLXIPL) were specifically amplified at higher frequencies in metastatic tumors." (PMID 26725848, 2016).
multiple myeloma (4 papers, 2018 to 2023). "A trial evaluating the effect of the PPARα agonist Fenofibrate on patients with multiple myeloma (NCT01965834) is ongoing." (PMID 30486822, 2018).
myopia (4 papers, 2019 to 2025). "In a form-deprivation myopia model, peribulbar injections of PPARα agonist inhibited FDM progression, while the PPARα antagonist induced a myopic shift and downregulated the scleral COL1 expression." (PMID 41224847, 2025).
pneumonia (4 papers, 2021 to 2023). An acute, acute and chronic, or chronic inflammation focally or diffusely affecting the lung parenchyma, caused by an infection in one or both of the lungs (by bacteria, viruses, fungi, or mycoplasma.). "Interestingly, while fenofibrates (PPARα agonist) are prescribed for abnormal blood lipid levels, infection and pneumonia are cited as possible adverse side effects and fenofibrate has been associated with higher risk of mortality in MTB infections." (PMID 35860381, 2022).
prostate tumor (4 papers, 2005 to 2022). "That study found NCoR1 to have diagnostic and prognostic significance in prostate tumor samples via antagonizing PPARα/γ signaling." (PMID 23669876, 2013).
adrenoleukodystrophy (3 papers, 2009 to 2023). A peroxisomal disorder resulting in cerebral demyelination, axonal dysfunction in the spinal cord leading to spastic paraplegia, adrenal insufficiency and in some cases testicular insufficiency. "The PPARα agonist fenofibrate has also been shown to activate SREBF2 and to have therapeutic potential for the treatment of adrenoleukodystrophy, consistent with the possibility that this drug may stimulate myelination." (PMID 27462272, 2016). "In humans, the importance of VLCFA-CoAs in PPARα activation was evident in adrenoleukodystrophy where there is accumulation of VLCFA in the cytosol, but no peroxisome formation of VLCFA-CoA and no hyperactivation of PPARα." (PMID 20300478, 2009).
allergic asthma (3 papers, 2015 to 2024). A asthma with a basis in a pathological type I hypersensitivity reaction. "Additionally, activation of PPARα with fenofibrate provides anti-inflammatory activity in allergic asthma." (PMID 25969669, 2015). "The knockout of the PPARα gene could increase the disease phenotype in an allergic asthma model." (PMID 38297226, 2024).
carnitine deficiency (3 papers, 2018 to 2021). "Evidence for this essential role of PPARα on carnitine homeostasis was confirmed in hepatocytes overexpressing PPARα and in PPARα-null mice, the latter which mice developed carnitine deficiency as a result of decreased hepatic γ-BBH and OCTN2 expression." (PMID 30002928, 2018).
carotid atherosclerosis (3 papers, 2023 to 2024). A thickening and loss of elasticity of the walls of carotid arteries that occur with formation of atherosclerotic plaques. "In present study, we found that PPARA rs4253655 was also associated with carotid atherosclerosis, thereby indicating its key role in the different stages of carotid atherosclerosis." (PMID 37292135, 2023). "However, studies on the potential relationship between PPARA SNPs and carotid atherosclerosis are lacking in the literature." (PMID 37292135, 2023). "Univariate analyses revealed there were significant differences in genotype distribution of PPARA rs4253655, IL1A rs1609682, and HABP2 rs7923349 between subjects with and without carotid atherosclerosis (p < 0.05)." (PMID 38827573, 2024). "Moreover, univariate analyses showed that there were significant differences in genotype distributions of IL1A rs1609682, PPARA rs4253655, and HABP2 rs7923349 between individuals with and without carotid atherosclerosis (p < 0.05)." (PMID 37292135, 2023).
celiac disease (3 papers, 2016 to 2022). An autoimmune genetic disorder with an unknown pattern of inheritance that primarily affects the digestive tract. "Conversely, disruption of PPARα and fatty acid oxidation is found in celiac disease, a condition characterized by shortened villi and malabsorption." (PMID 34857752, 2021). "Another finding from this study was the down-regulation of mRNA levels of both PPARA and PPARG in celiac disease children as compared with controls." (PMID 27483138, 2016).
colorectal adenocarcinoma (3 papers, 2019 to 2025). The most common type of colorectal carcinoma. "The biological examples included in this study demonstrate the practical usefulness of LoQANT in quantifying nuclear staining of PPARα and phospho-p38 in colorectal adenocarcinoma-derived HT-29 cells." (PMID 41226833, 2025).
coronary atherosclerosis (3 papers, 2022 to 2025). Atherosclerosis of the coronary vasculature. "Consequently, TBL1XR1 modulated TG metabolism by regulating PPARα expression, thereby contributing to the initiation and development of coronary atherosclerosis." (PMID 41476864, 2025). "In addition, PPARα reduces serum cholesterol and LDL levels by regulating cholesterol 7A-hydroxylase, sterol 12a-hydroxylase, increases the level of high-density lipoprotein (HDL), hydrolyzes very low-density lipoprotein (VLDL), and delays the progression of coronary atherosclerosis." (PMID 36420262, 2022).
cystic fibrosis (3 papers, 2006 to 2007). Autosomal recessive disorder caused by pathogenic variants in the CFTR gene (cystic fibrosis transmembrane conductance regulator), which encodes a chloride and bicarbonate channel expressed in epithelial cells, and follow the diagnosis criteria. "Recent reports have found significantly reduced PPARα mRNAlevels in lymphocytes from cystic fibrosis patients,while PPARα knockout mice develop more severecarageenan-induced pleural inflammation, suggesting aconnection between diminished PPARα-dependent gene activationand disease pathology." (PMID 17710235, 2007). "PPARα and PPARβ were expressed in peripheral blood lymphocytes, monocytes, and neutrophils healthy subjects and in patients with cystic fibrosis." (PMID 18000530, 2007).
cystic kidney (3 papers, 2017 to 2024). "Concordantly, the genes encoding PPARα and estrogen-related receptors (PPARGC1A, PPARA, ESRRA and ESRRG) were all downregulated in renal cysts." (PMID 39000280, 2024). "Collectively, these observations suggest that miR-17 promotes proliferation in cystic kidneys, at least in part, by reprogramming metabolism through direct repression of Pparα." (PMID 28205547, 2017). "Other transcriptional regulators that were predicted to be most inhibited in renal cysts included PGC-1α (z-score = −4.9), PPARα (z-score = −3.4) and ERRα (z-score = −3.2)." (PMID 39000280, 2024).
diabetic neuropathy (3 papers, 2021 to 2025). A chronic, pathological complication associated with diabetes mellitus, where nerve damages are incurred due to diabetic microvascular injury involving small blood vessels that supply these nerves, resulting in peripheral and/or autonomic nerve dysfunction. "For diabetic neuropathy, gene GFY (rs4802605), ADH4 (rs4148883), LRFN2 (rs61731010), PKHD1 (rs2499486), SLC11A1 (rs17235409), MATN4 (rs2072788), and PPARA (rs4253772) were associated or contributed to the biological relevance to the pathogenesis of the complication." (PMID 37033211, 2023). "The PPARA gene has been associated to immune and inflammatory responses, as well as lipid markers, glycolytic markers, T2DM and anthropometric measurements, such as waist-to-hip ratio and body mass index, all relevant risk factors for diabetic neuropathy." (PMID 37033211, 2023). "In humans, the endogenous PPARα agonist PEA shows great efficacy in the treatment of various human pain conditions, including diabetic neuropathy, sciatic pain, and postoperative pain." (PMID 33552153, 2021).